GNPDA2 (glucosamine-6-phosphate deaminase 2)
Diseases named in the same sentence as GNPDA2 in open-access papers:
GNPDA2 is named in the same sentence as 22 diseases in open-access papers, as found by Europe PMC text mining. Sharing a sentence is not in itself a finding about the gene and the disease. The quoted sentences say what the papers report.
Obesity (45 papers, 2010 to 2025). Accumulation of substantial excess body fat. "GNPDA2 is linked to lipid metabolism and obesity, with sleep duration influencing genetic susceptibility to obesity through the leptin pathway." (PMID 40024983, 2025). "The GNPDA2 gene is associated with a greater body mass index and obesity, while colorectal cancer, hepatocellular, and other gastrointestinal malignancies show increased GNPDA1 protein levels; the latter is addressed in the next section." (PMID 39596123, 2024). "Nearly all the reports linking GNPDA2 with obesity are based on genome-wide association studies (GWASs) conducted in different populations worldwide." (PMID 39596123, 2024). "Genome-wide association studies (GWAS) have revealed an association of GNPDA2 with human obesity, as well as with type-2 diabetes." (PMID 34912841, 2021). "For this reason, our interest to understand the function of new genes associated with obesity and type 2 diabetes led us to analyze GNPDA2 expression in the hypothalamus of diet-induced obese rats showing it is down-regulated." (PMID 34912841, 2021). "Several obesity susceptibility loci in genes, including GNPDA2, SH2B1, TMEM18, MTCH2, CDKAL1, FAIM2, and MC4R, have been identified by genome-wide association studies." (PMID 32228543, 2020). "The genes reviewed here are FTO, NRXN3, NPC1, NEGR1, MTCH2, and GNPDA2, which were chosen for their association with obesity and their influence on NDgD or NDvD." (PMID 32982666, 2020). "The function of GNPDA2 remains to be further studied to help elucidate the pathogenic role of the gene in obesity." (PMID 31467530, 2019). "We found a significant effect of GNPDA2 rs10938397 on risk of obesity (odds ratio [OR] = 1.30; P = 1.34 × 10-3)." (PMID 23375129, 2013). "From our study based on obese and nonobese Mexican children, we found a significant contribution of the minor allele of GNPDA2 rs10938397 to increased risk of obesity." (PMID 23375129, 2013). "Both the ETV5 rs7647305 C-allele and the GNPDA2 rs10938397 A-allele associated with increased risk of obesity with ORs 1.18 (1.08–1.29, p = 1.8×10−4) (rs7647305) and 1.15 (1.07–1.23, p = 1.1×10−4)) (rs10938397), but not with overweight or morbid obesity." (PMID 21912638, 2011). "GNPDA2 has also been reported to be associated with influencing BMI and susceptibility to obesity." (PMID 36035367, 2022). "GNPDA2 has been reported to be associated with influencing BMI and susceptibility to obesity." (PMID 36035367, 2022). "GNPDA2 has been associated with human obesity and type-2 diabetes by using a GWAS approach." (PMID 34912841, 2021). "An association of GNPDA2 with obesity and type-2 diabetes or both, has been reported in humans." (PMID 34912841, 2021). "Several genes among this gene set were associated with obesity, including GNPDA2, MTHFR, and ATF4." (PMID 29854750, 2018). "When further adjusted for BMI, the obesity predisposing loci, GNPDA2-rs16858082 (P = 0.016) and PCSK1-rs261967 (P = 0.026) were still nominally associated with total cholesterol (TC) levels, and MC4R-rs2331841 remained correlated with fasting glucose (FBG) levels (P = 0.012)." (PMID 29212175, 2017). "Further meta-analysis involving previous and current studies in Chinese populations supported the findings of the current study, which suggests the effect of GNPDA2 on type 2 diabetes risk may be mediated through obesity." (PMID 25093408, 2014). "In studies conducted in adults, SNPs in the genes FTO, MC4R, TMEM18, TNNI3K, SEC16B, GNPDA2, and POMC are strongly associated with obesity risk." (PMID 40722558, 2025). "In the Asian context, a GWAS study from a Japanese sample found two significant obesity-related variants in SEC16B (rs10913469) and GNPDA2 genes." (PMID 40024983, 2025).
Obesity (continued). "In summary, GNPDA2 promotes lipogenesis and adipocyte proliferation, which is in accordance with the weight gain and obesity found in multiple GWAS and epidemiologic studies; however, in the central nervous system, this enzyme does not increase food intake." (PMID 39596123, 2024). "Herein, we focused on four ORGs: fat mass and obesity-associated (FTO), melanocortin-4 receptor (MC4R), glucosamine-6-phosphate deaminase 2 (GNPDA2), and transmembrane protein 18 (TMEM18)." (PMID 36289871, 2022). "Of the identified genes in our study, FTO, GNPDA2, MC4R, MTCH2, NEGR1, SH2B1, TMEM18 are unequivocally regarded as obesity genes associated with PCOS, as supported by contemporary evidence." (PMID 35679284, 2022). "Associations of the loci SH2B1 (rs7498665), near GNPDA2 (rs10938397), MTCH2 (rs10838738), and near MC4R (rs12970134) with obesity have been shown in many studies." (PMID 32228543, 2020). "In a diet-induced obesity model, high-fat diet led to a lower GNPDA2 hypothalamic expression compared to rats fed with chow diet." (PMID 32982666, 2020). "Among those identified SNPs, the SNP rs10938397, located near the glucosamine-6-phosphate deaminase 2 gene (GNPDA2), showed a significant association with obesity in Chinese adults and children." (PMID 31467530, 2019). "Two loci significantly associated with obesity in Qataris: the TFAP2B variation (rs987237) (A allele versus G allele: chi-square = 10.3; P = 0.0013) and GNPDA2 variation (rs10938397) (A allele versus G allele: chi-square = 6.15; P = 0.013)." (PMID 25890290, 2015). "In the present study, we identified the association of obesity-related SNPs, rs12970134 near MC4R, rs10938397 near GNPDA2, and rs2260000 within BAT2, with the susceptibility of type 2 diabetes in a large Han Chinese population." (PMID 25093408, 2014). "Two other obesity associated genes, MC4R and GNPDA2 were also identified by GWAS in Europeans and replicated in other studies." (PMID 23424664, 2013). "The association of six European obesity-related SNPs in or near FTO, NPC1, ENPP1, NEGR1, GNPDA2 and MC4R genes with risk of obesity was tested in 1,463 school-aged Mexican children (Ncases = 514; Ncontrols = 949)." (PMID 23375129, 2013). "SNPs in the FTO, GNPDA2, SEC16B, BDNF, TMEM18 and NPC1 loci associated with increased risk of both overweight and obesity." (PMID 23861046, 2013). "Other loci, including the INSIG2, TMEM18, KCTD15, SH2B1, MTCH2, GNPDA2, BDNF, or CHST8 genes, have also been associated with obesity." (PMID 24267414, 2013). "The obesity-risk-allele score based on genotypes at eight SNPs associated with childhood BMI (in/near to: FTO, MC4R, TMEM18, GNPDA2, NEGR, KCTD15, BDNF, and ETV5) ranged from 2 to 15 alleles." (PMID 20520848, 2010). "In the same way, GNPDA2 can provide glycolytic precursors for tri-acyl glyceride synthesis, with this mechanism having been suggested as a possible explanation for the relationship between GNPDA2 and obesity." (PMID 39596123, 2024). "GNPDA1 is expressed in the brain to an even greater extent than GNPDA2; however, it is still unknown whether it plays any role in the metabolism of glucose in this organ in relation to obesity." (PMID 39596123, 2024). "Selected ORGs expression, namely the fat mass and obesity-associated (FTO), melanocortin-4 receptor (MC4R), glucosamine-6-phosphate deaminase 2 (GNPDA2), and transmembrane protein 18 (TMEM18) were evaluated in testes and spermatozoa by a quantitative polymerase chain reaction (qPCR)." (PMID 36289871, 2022). "The locus near GNPDA2 (rs10938397) was associated with increased risk for obesity, which was independent of BMI." (PMID 32228543, 2020). "Specific variants of GNPDA2, PGC1α and LEPR genes have shown a strong association with Mexican population’s BMI, increasing the risk of obesity, although the control mechanisms of obesogenic genes expression during early development are still unknown." (PMID 31794592, 2019).
Obesity (continued). "As obesity is accompanied by an increase in the size and the number of adipocytes, the present study investigates the possible mechanism of the GNPDA2 in adipogenesis using GeneChip® Human Transcriptome Array 2.0 in human adipose-derived mesenchymal stem cells." (PMID 31467530, 2019). "Given that adipocytes are thought to differentiate from adipose-derived mesenchymal stem cells (ADMSCs) and GNPDA2 is related to obesity, we constructed GNPDA2 overexpression and short hairpin RNA (shRNA) knockdown ADMSCs and analyzed the gene expression profiling." (PMID 31467530, 2019). "The effect of the genetic locus including GNPDA2 on type 2 diabetes might be mediated through obesity." (PMID 25093408, 2014). "In both studies, we genotyped six SNPs that are known to be associated with risk of obesity in European populations: rs17782313 near MC4R; rs2815752 near NEGR1; rs7754561 near ENPP1; rs1805081 in exon 6 of NPC1; rs10938397 near GNPDA2 and rs1421085 in intron 1 of FTO." (PMID 23375129, 2013). "For other cardiometabolic traits, the obesity predisposing locus, FTO-rs1558902 yielded significant association with systolic blood pressure (SBP) (P = 0.001), while the risk alleles of SNPs in/near GNPDA2, PCSK1 and MAP2K5 yielded nominal association with blood pressures (P < 0.05)." (PMID 29212175, 2017). "The expression level of each of the five obesity-related genes (SH2B1, GNPDA2, FTO, TMEM18, and KCTD15) in three cancer tissues (HNSC, LIHC, and CHOL) was higher than that in the corresponding normal tissues." (PMID 33299884, 2020). "The expression levels of other eight obesity-related genes (TMEM18, KCTD15, GNPDA2, SH2B1, FTO, LEP, PCSK1, and GPR120) in about half types of cancer tissues were higher/lower than those in the corresponding normal tissues." (PMID 33299884, 2020). "In summary, in our sample of Chinese children, we replicated eight adult East Asian obesity-related loci (in/near FTO, MC4R, GNPDA2, PCSK1, SEC16B, MAP2K5, ITIH4 and BDNF) in the same direction of effect as previous reports in adults." (PMID 29212175, 2017). "In race/ethnic-specific analyses, we identified a number of genes related to obesity (GNPDA2, ZNF664-FAM101A, PFKP, SAMD4A), glycosylation (GYPC, FUT10), and carbohydrate metabolism (GNPDA2, PFKP, SLC45A)." (PMID 28521775, 2017). "Human SCs express obesity-related genes (ORG, MC4R, GNPDA2, TMEM18, and FTO), and the expression of GNPDA2 and TMEM18 proteins in SCs has been reported to increase after incubation with leptin and ghrelin, leading to a modulation of the nutritional support provided for spermatogenesis." (PMID 38961093, 2024). "Moreover, recent reports of obesity-related loci enriched in brain-expressed genes such as FTO, MC4R, GNPDA2, and BDNF point to a neuronal influence on body weight regulation in adults." (PMID 29212175, 2017). "However, the molecular mechanisms of the expression of GNPDA2 involved in obesity are not understood." (PMID 31467530, 2019). "Due to the nature of these studies (primarily meta-analyses), they do not provide insights into the possible mechanisms by which GNPDA2, as an enzyme or protein, could be involved in the pathology of obesity; however, the few experimental publications in this field provide valuable data." (PMID 39596123, 2024). "Additionally, other causal genes are highly expressed or known to act in human brain function (i.e., NEGR1, GNPDA2, CYP46A1, DGKH) and various carcinomas (i.e., PMAIP1, HORMAD1, FES, BCAS3), indicating the potential role of metabolic dysregulation in the pathogenesis of obesity and cardiac events." (PMID 33910581, 2021).
type 2 diabetes (6 papers, 2011 to 2024). "Overall, these results indicate the involvement of the GNPDA2 isoenzyme in the metabolic changes underlying type 2 diabetes and some other related pathologies such as NAFLD." (PMID 39596123, 2024). "In particular, the current results provide a potential explanation for the observation that GNPDA2 polymorphisms are associated with increased risk of type 2 diabetes." (PMID 34912841, 2021). "After adjustment for age and sex, two SNPs near the MC4R (rs12970134) and GNPDA2 (rs10938397) genes were found to be significantly associated with type 2 diabetes (P = 4.75×10−4 and 4.54×10−3, respectively)." (PMID 25093408, 2014). "Meta-analysis of the association between SNPs near MC4R, GNPDA2 and risk for type 2 diabetes risk in Chinese populations." (PMID 25093408, 2014). "It is important to recall that there is no direct evidence that the SNP rs10938397 alters endogenous GNPDA2 expression in adipose tissue; however, changes in glucose homeostasis could be associated with a higher risk of type 2 diabetes." (PMID 39596123, 2024). "Finally, we performed meta-analysis that combined previous studies and present findings to provide more precise estimates for the effect of MC4R and GNPDA2 on the risk for type 2 diabetes." (PMID 25093408, 2014). "We identified five additional studies which examined the associations of rs12970134 or its proxy SNP rs17782313 near MC4R with type 2 diabetes and two additional studies examining the associations of rs10938397 near GNPDA2 with type 2 diabetes, all in populations of Han Chinese." (PMID 25093408, 2014). "At the locus near GNPDA2 (rs10938397), the AA genotype was most abundant in patients with overweight and type 2 diabetes (50.0%), and GG was most abundant in healthy controls (21.1%)." (PMID 32228543, 2020). "The risk of type 2 diabetes has only been addressed in two other studies, and here association between TMEM18, GNPDA2, ETV5, FAIM2 and SH2B1 and a BMI-dependent increased risk of type 2 diabetes have been reported." (PMID 21912638, 2011). "We did not observe any significant associations of the three type 2 diabetes-associated SNPs (rs12970134 near MC4R, rs10938397 near GNPDA2, and rs2260000 within BAT2) with these quantitative glycemic traits (all P values>0.05)." (PMID 25093408, 2014). "After adjusting for sex and age, loci near TMEM18 (rs6548238) and FAIM2 (rs7138803), but not SH2B1 (rs7498665), near GNPDA2 (rs10938397), MTCH2 (rs10838738) and near MC4R (rs12970134), were associated with increased risk for type 2 diabetes in obese individuals." (PMID 32228543, 2020).
Insulin resistance (2 papers, 2016 to 2022). Increased resistance towards insulin, that is, diminished effectiveness of insulin in reducing blood glucose levels. "ETV5 modulates circulating glucocorticoids levels and GNPDA2 regulates metabolic pathways leading to insulin resistance." (PMID 27788139, 2016).
amyotrophic lateral sclerosis (1 paper, 2024). Amyotrophic lateral sclerosis (ALS) is a neurodegenerative disease characterized by progressive muscular paralysis reflecting degeneration of motor neurons in the primary motor cortex, corticospinal tracts, brainstem and spinal cord. "In humans, a significant increase in serum GNPDA2 levels was observed across multiple neurological proteinopathies (AD, Lewy body dementia, progressive supranuclear palsy, mixed dementia and amyotrophic lateral sclerosis) (n = 215)." (PMID 38672412, 2024).
central obesity (1 paper, 2013). "Our study presents the new evidence that FTO rs9939609, MC4R rs17782313, GNPDA2 rs10938397 and BDNF rs6265 are statistically significantly associated with risk of central obesity in the Chinese children." (PMID 23424664, 2013). "The joint effect of four strongly associated SNPs (FTO rs9939609, MC4R rs17782313, GNPDA2 rs10938397, BDNF rs6265) on the risk of central obesity was further investigated." (PMID 23424664, 2013). "Our study replicates the statistically significant association of four SNPs (FTO rs9939609, MC4R rs17782313, GNPDA2 rs10938397, BDNF rs6265) with risk of central obesity in the Chinese children." (PMID 23424664, 2013). "The results indicated that four SNPs (FTO rs9939609, MC4R rs17782313, GNPDA2 rs10938397, BDNF rs6265) and GRS calculated from these 4 SNPs significantly predicted the risk of central obesity." (PMID 23424664, 2013). "In conclusion, our study confirmed the significant association of four SNPs (FTO rs9939609, MC4R rs17782313, GNPDA2 rs10938397, BDNF rs6265) with risk of central obesity in the Chinese children." (PMID 23424664, 2013). "A 12-year longitudinal study showed that FTO rs8050136 and GNPDA2 rs10938397 SNPs, rather than MC4R rs17782313, predicted persistent central obesity in the Chinese adults." (PMID 23424664, 2013).
Glucose intolerance (1 paper, 2021). Glucose intolerance (GI) can be defined as dysglycemia that comprises both prediabetes and diabetes. "The GNPDA2 inhibitor could lead to increased flux through GlcN-6-P, being a plausible mechanism how this substance is leading to glucose intolerance and should be demonstrated in the future." (PMID 34912841, 2021). "However, central inhibition of GNPDA2 did provoke significant glucose intolerance." (PMID 34912841, 2021). "In addition, central administration of the GNPDA2 antagonist, prior to an intraperitoneal glucose tolerance test, resulted in glucose intolerance in comparison to vehicle without altering insulin levels." (PMID 34912841, 2021). "Interestingly, central inhibition of GNPDA2 provoked significant glucose intolerance without changes in plasma insulin levels." (PMID 34912841, 2021).
osteosarcoma (1 paper, 2021). A usually aggressive malignant bone-forming mesenchymal neoplasm, predominantly affecting adolescents and young adults. "The selected 5 MAGs (MAP3K5, PML, WDR1, BAMBI, and GNPDA2) were identified as prognostic-related genes for osteosarcoma, and a novel macrophage-associated risk model was constructed based on these 5 MAGs." (PMID 34188683, 2021). "In general, 5 MAGs (MAP3K5, PML, WDR1, BAMBI, and GNPDA2) correlated with the prognosis of osteosarcoma were screened for the construction of the risk model." (PMID 34188683, 2021). "Gene WDR1 (p = 0.003), PML (p = 0.002), MAP3K5 (p < 0.001), and GNPDA2 (p = 0.030) showed a better prognosis of osteosarcoma in the high expression group." (PMID 34188683, 2021). "The expression of gene WDR1 (p = 0.006), PML (p = 0.005), MAP3K5 (p = 0.010), and GNPDA2 (p = 0.009) were significantly higher in normal bone sample while in osteosarcoma samples, the expression of BAMBI (p = 0.006) was significantly higher." (PMID 34188683, 2021).
cancer (3 papers, 2020 to 2024). A tumor composed of atypical neoplastic, often pleomorphic cells that invade other tissues. "For instance, for GNPDA2 gene in LIHC patients, four clinical factors (gender (P = 1.1E − 3), race (P = 1E − 4), tumor grade (P = 4.4E − 2), and BMI (P = 2.1E − 2)) influenced the Kaplan–Meier survival curves in cancer tissues with different expression levels of the GNPDA2 gene." (PMID 33299884, 2020).
cardiovascular disease (1 paper, 2021). "An animal study also suggested that GNPDA2 was involved in the regulation of body weight, fat and energy metabolism in the development of cardiovascular disease." (PMID 33910581, 2021).
GNPDA2 also shares sentences with these, for which no sentence is quoted: tumor (2 papers); asthma (1); breast carcinoma (1); diabetes mellitus type 2 (1); frontotemporal dementia (1); Hypercholesterolemia (1); Lewy body dementia (1); morbid obesity (1); multiple sclerosis (1); neurodegenerative disease (1); Niemann-Pick disease, type C1 (1); Parkinson disease (1); progressive supranuclear palsy (1).